LEP (leptin)
Diseases named in the same sentence as LEP in open-access papers (continued):
Sharing a sentence is not in itself a finding about the gene and the disease.
cancer (continued). "The most important issue in modulating leptin pathways is to achieve target specificity since this adipokine does not only influence cancer tissues, but it is implicated in a wide spectrum of physiological processes in peripheral organs as well as in the central nervous system." (PMID 25721149, 2015). "For example, it remains to be determined whether decreased leptin levels indicate the loss of visceral or subcutaneous adipose tissue in cancer." (PMID 26508820, 2015). "Chronically elevated endogenous leptin levels may be one mechanism for NK cell dysfunctions and consecutive increased cancer susceptibility in obese humans." (PMID 26217516, 2015). "To test our hypothesis that leptin causes growth of cancer cells through autophagy induction, we first assessed the effect of leptin on autophagy induction." (PMID 25704884, 2015). "The leptin:adiponectin ratio is also an important indicator of cancer risk." (PMID 25072025, 2014). "Furthermore, we demonstrated, for the first time, that higher leptin levels assayed years long before cancer diagnosis were significantly associated with an increased risk of OVC." (PMID 25115836, 2014). "Second, excessive sitting time could increase levels of inflammatory factors such as tumor necrosis factor-α, interleukin-6, and leptin which are known risk predictors for cancer." (PMID 25153314, 2014). "The leptin:adiponectin ratio is an important indicator of cancer risk." (PMID 25072025, 2014). "The activated signaling pathway and proteins formed by LEP-LEPR linking has been associated with cancer pathogenesis due to interactions with Janus kinase tyrosine (JAK-2), suppressors of cytokine signaling (SOCS), and the signal transducer and activator of transcription-3 (STAT)." (PMID 26034683, 2014). "Likewise, previous reports also demonstrated that LEP 2548AA was associated with an increased risk of cancer; however, replication of this finding by others also failed as well." (PMID 24146750, 2013). "Meta-analysis of the association between LEP G2548A polymorphism and cancer risk." (PMID 24146750, 2013). "This may imply that there is an underlying shift in leptin-induced cell signaling pathways in cancer cells." (PMID 24202338, 2013). "Second, the gene-encoding leptin has been linked to the growth and development of cancer." (PMID 24198829, 2013). "Familial predisposition to cancer represented by individuals harbouring certain genetic defects, might strengthen the carcinogenesis role of LEP gene family, therefore, create a hot bed for tumor." (PMID 23593308, 2013). "Leptin has been identified in several types of human cancers and may also be linked to poor prognosis." (PMID 21338489, 2011). "In addition, increased adiposity is associated with increased levels of potentially cancer-promoting adipokines, such as leptin, and decreased levels of potential anticancer adipokines, such as adiponectin." (PMID 22017857, 2011). "This hypothesis is further strengthened by other groups who observed increased leptin levels in NSCLC patients and recognized leptin as a risk factor for cancer, even after controlling for BMI and recent weight loss." (PMID 21040518, 2010). "We also found a correlation between leptin levels and cancer-induced weight loss." (PMID 20920199, 2010). "It has been recently suggested that adipocytokines, such as TNF–alpha, IL–6, type–1 plasminogen activator inhibitor (PAI–1), adiponectin, leptin, resistin, visfatin and apelin are associated with the risk of cancer at various sites (e.g., breast, prostate gland, endometrium and colorectum)." (PMID 21254741, 2010). "Leptin's pleiotropic effects are linked to diverse processes that if de-regulated could contribute to the growth of cancer; that is, proliferation, anti-apoptosis, angiogenesis, extracellular membrane component changes and metastasis." (PMID 19531256, 2009).
cancer (continued). "Also, higher leptin concentrations in the pancreatic and pulmonary locations may indicate different roles of leptin in the cancer pathogenesis and its involvement in cancer-linked systemic inflammation." (PMID 39337308, 2024). "However, the relationship between leptin levels and cancer risk remains ambiguous." (PMID 38534454, 2024). "Several hormones and cytokines, such as leptin, ghrelin, interleukin (IL)-1β, IL-6, and tumor necrosis factor alpha, contribute to the inflammation-mediated loss of fat and muscle and actively participate in the homeostasis of muscle and fat tissues in patients with cancer." (PMID 35203597, 2022). "Both direct and indirect effects of leptin in regulating cancer proliferation, metastasis, angiogenesis, and chemoresistance have been identified, and leptin—either alone or in combination with other adipokines and cytokines—has been identified as a biomarker of cancer risk." (PMID 35454071, 2022). "Interestingly, several short-term randomized clinical trials have indicated promising effects of alternate day fasting or a 5:2 diet in improving some cancer risk factors, including decreased fasting glucose, insulin, and leptin levels and increased adiponectin." (PMID 35984550, 2022). "Moreover, LEP is involved in immune activity exhaustion associated with low chronic inflammation in obese cancer patients, which could be employed to improve the response to immune checkpoint inhibitors." (PMID 36291602, 2022). "In addition, normal and pathological levels of leptin and adiponectin should be clearly defined, as their assessment could be useful to clinicians for a better definition of risk categories of cancer and other chronic conditions." (PMID 34209441, 2021). "The potential role of leptin in tumor evasion and metastasis was also explained by different mechanisms that involve tumor progression and migration, including not only signaling pathways, but also cancer-associated fibroblasts, VEGF and TAMs, among many others." (PMID 34202969, 2021). "Indeed, leptin is closely associated with cytokine levels, mainly IL-6, and has been identified as a mediator of the metabolic and immunological changes observed in advanced cancer patients." (PMID 33809200, 2021). "This meta-analysis revealed that the LEP G19A polymorphism may decrease the risk of cancer." (PMID 34868961, 2021). "Overall, we found a significant correlation between the LEP G19A mutation and susceptibility to cancers under four models (allele model, dominant model, recessive model, and homozygote model), which means that this mutation may decrease the risk of overall cancer." (PMID 34868961, 2021). "Growing evidence indicates that the adipokine leptin, a pleiotropic molecule encoded by the obese gene originally known for its role as a regulator of food intake and energy balance in the mammalian central nervous system, plays a crucial role in maintaining cancer in a stem-like state." (PMID 32526957, 2020). "In addition to elevated leptin levels, some studies indicate that mutations in leptin, ObR, and signaling pathways are important objects of study to comprehend multiple diseases such as cancer." (PMID 33334030, 2020). "In the inflammatory context, leptin may promote molecular changes capable of modulating the behavior of tumor cells and the surrounding microenvironment, which include cancer and adipose-derived stem cells, cancer-associated adipocytes, epithelial cancer cells, fibroblasts and also immune cells." (PMID 32824322, 2020). "Increased levels of hormones (such as oestrogen, insulin, insulin-like growth factor, and leptin), free fatty acid-induced production of reactive oxygen species, an altered intestinal microbiome and chronic inflammation are known to be associated with an increased cancer risk in obese subjects." (PMID 31439906, 2019). "It was found that LEP G19A polymorphism may have a lower risk of overall cancer." (PMID 30697798, 2019).
cancer (continued). "The increased expression of MEK and phosphorylated ERK and the concomitant decrease in IGF2 and IGF-1R expression in co-culture conditions might also indicate a shift from the endogenous paracrine IGF2 axis towards a cancer promoting ASC-associated leptin axis." (PMID 31817072, 2019). "Furthermore, the fact that MCF10a cells undergo EMT-associated events upon leptin stimulation might be a good reflection of the early events that occurs during cancer and metastasis progression." (PMID 31554180, 2019). "Therefore, it is possible that leptin, despite being weakly associated to cancer incidence, may reflect susceptibility for fatal malignancies." (PMID 26632325, 2016). "In addition, the LEP gene has been linked to the other physiologic and pathologic mechanisms, such as bone remodeling, inflammation, rheumatoid arthritis and the development of some cancers." (PMID 26034683, 2014). "Given the potential role of Leptin gene family in carcinogenesis and the influence of genetic polymorphisms in regulation of gene expression and function, it is inferred that polymorphisms in this gene family might exert an influence on cancer susceptibility." (PMID 23593308, 2013). "Earlier studies demonstrated that leptin supports cancer progression by modulating various carcinogenesis mechanisms, including cell cycle regulation, secretion of angiogenic proteins, and enhancing migration." (PMID 41562922, 2026). "Consistent with observations demonstrating the capacity of leptin to promote invasiveness in various cancers, the wound-healing and tumor spheroid dissemination assays used here further validate leptin’s role in promoting migratory behavior in BC cells." (PMID 41562922, 2026). "GPR50 plays roles in various physiological processes, including cancer progression, Notch signaling, and insulin, leptin, and glucocorticoid signaling." (PMID 41666959, 2026). "Dysregulation of adipose tissue leads to abnormal secretion of leptin and adiponectin, hormones that also play roles in cancer development." (PMID 41560111, 2026). "Although the role of leptin in cancer cachexia is controversial, it is believed to participate in its pathogenesis." (PMID 39764565, 2025). "Given these signaling cascades, leptin plays a central role in fostering an environment conducive to cancer development and progression." (PMID 40387523, 2025). "The reduction of leptin and stimulation of adiponectin can contribute to the anti-cancer effects of SGLT2is." (PMID 39941833, 2025). "In gastric cancer, leptin has been shown to stimulate migration and invasion of cancer cells by activating the JAK-STAT and MEK pathways." (PMID 40722646, 2025). "Both leptin and the Ob‐R have been detected in various malignant tumors, including those of the thyroid, breast, and colorectal regions." (PMID 40620232, 2025). "Leptin depletion should be considered when using ob/ob mice, as leptin is important in cancer-stromal crosstalk and is upregulated in obese ASCs." (PMID 40847127, 2025). "Screened molecules displayed an overall balanced distribution among the three cancer subgroups, with the exception of a slight increase of IL-12 in PC patients, and a remarkably higher concentration of Leptin in BC patients." (PMID 41409302, 2025). "In contrast, high adipose tissue levels provide a survival advantage for patients with cancer, as subcutaneous adipose is metabolically stable and produces leptin, improving insulin sensitivity." (PMID 40385349, 2025). "Abnormal leptin signaling has been documented in several cancers, including those of the breast, endometrium, pancreas, colon, prostate, liver, skin, brain, esophagus, stomach, thyroid gland and ovaries, as well as in leukemia and some bone cancers." (PMID 40095546, 2025). "Adipocytes release leptin, a pro-inflammatory substance that stimulates cancer cell proliferation, inflammation, and invasion, altering the tumor cell metabolic pathway." (PMID 40040878, 2025).
cancer (continued). "Chronic sleep disruption has been shown to affect hormones like leptin and ghrelin, which regulate appetite and energy balance, potentially promoting weight gain and metabolic changes conducive to cancer development." (PMID 40283700, 2025). "Leptin resistance is particularly relevant in cancer cachexia, where elevated leptin levels fail to restore appetite due to SOCS3-mediated inhibition of LepRb signaling." (PMID 40704145, 2025). "Although leptin plays an important role in inflammation and cancer development, it has a beneficial effect in enhancing the efficacy of cancer immunotherapy." (PMID 40863244, 2025). "Given the well-established association between STA3 and tumor progression, we investigated the impact of leptin present in OB EVs on key stages of cancer development." (PMID 40485730, 2025). "The imbalance between high leptin and low adiponectin, coupled with the systemic inflammation from IR, creates a pro-tumorigenic environment that is highly conducive to cancer initiation and progression." (PMID 41002547, 2025). "Leptin promotes cancer cell progression and metastasis by tumor cell proliferation induction and cancer cell apoptosis inhibition via Wnt5a/JNK, STAT3/5 and MAPK/ERK1/2 pathways activation." (PMID 40227577, 2025). "Given that AKT is a central regulator of cancer cell metabolism, these results suggest it is a key molecular link connecting leptin signaling, FAO, and enhanced tumor cell migration." (PMID 40485730, 2025). "Hormones derived from adipose tissue, such as leptin and adiponectin, also exert pleiotropic effects on cancer cells, modulating cellular processes such as proliferation, apoptosis, angiogenesis, and immune surveillance." (PMID 40040878, 2025). "The growing list of leptin/leptin receptor targets has shortened the gap between our understanding of inflammation, metabolism and cancer and will offer novel avenues for drug intervention." (PMID 40095546, 2025). "Building upon the understanding that leptin facilitates the migration and invasion of cancer cells through the JAK2/STAT3 signaling pathway, we investigated the influence of leptin within OB EVs on these critical stages of tumor metastasis." (PMID 40485730, 2025). "Within the TME, CAFs exhibit heightened lipid metabolic activity, secreting fatty acids and lipid factors like leptin to provide additional energy for rapidly proliferating cancer cells." (PMID 40391753, 2025). "• An inverse association exists for additional steps and lower insulin and leptin metabolic biomarkers in cancer survivors." (PMID 40783771, 2025). "In cancer cachexia, leptin is produced by adipose tissue and acts on the hypothalamus to regulate energy storage by influencing appetite." (PMID 39764565, 2025). "It has been proposed that dysfunctional WAT contributes to the pathophysiology of cancer by raising systemic levels of leptin, steroid hormones, insulin, and insulin‐like growth factor‐1 (IGF‐1) while lowering the concentration of adiponectin." (PMID 39496581, 2025). "Cellular metabolism dysregulation is a defining feature of cancer, with leptin playing a pivotal role in mediating this alteration." (PMID 40485730, 2025). "Marrow adipocytes and adipokines (e.g., leptin and adiponectin) promote cancer cell migration and survival." (PMID 40224177, 2025). "Elevated Leptin: This pro-inflammatory adipokine promotes cancer cell proliferation, angiogenesis, and metastasis, partly by activating the PI3K/Akt and MAPK signaling pathways." (PMID 41002547, 2025). "One study found that leptin, an adipocytokine known to have increased levels during cancer development, impaired natural killer cell cytotoxicity." (PMID 40722609, 2025). "Beyond its established roles in appetite regulation and body weight control, leptin significantly influences cancer biology." (PMID 40565190, 2025). "Leptin is considered to promote cancer by directly stimulating cancer cells and by modulating anti-cancer immune responses." (PMID 39941833, 2025).
cancer (continued). "Leptin has been proved to promote the progression of multiple cancers, such as BC, blood cancer and CRC." (PMID 40248695, 2025). "Recent studies have identified leptin as a key modulator in cancer progression by promoting proliferation, angiogenesis, invasion, and metastasis, as well as by modulating immune responses and inflammation." (PMID 40387523, 2025). "Adiponectin and leptin are adipokines with relatively detailed mechanisms and abundant epidemiological data, especially in cancer cell growth." (PMID 39201655, 2024). "Adipokines released by adipocytes, such as IL-6 and leptin, are crucial for the promotion of chemotherapeutic resistance in cancer cells." (PMID 38302980, 2024). "A positive correlation was observed with increased malignancy of different cancer subtypes and leptin expression." (PMID 38418632, 2024). "Further, the expression of leptin and its receptor is positively correlated with cancer invasiveness indicators including tumor size and LNM." (PMID 38800384, 2024). "The anti-apoptotic effect of leptin on cancer cells is also mediated through NF-κB inducing proliferation, differentiation, metastasis, angiogenesis, and chemoradiotherapy resistance in cancer cells." (PMID 38611081, 2024). "More recently, expression of both leptin and its receptor has been documented in cell types besides adipocytes that include cancer cells, suggesting a possible role in cancer signaling." (PMID 38418632, 2024). "A three-dimensional culture VM formation assay was performed to determine the potential of leptin to form vascular channels by cancer cells." (PMID 38791252, 2024). "As for the impact of leptin on various cancer cells, both inhibitory and stimulatory effects have been observed." (PMID 39201370, 2024). "Of note, this T cell–exhausted phenotype was partially mediated by leptin, highlighting a potential crosstalk between AT and immune responses to cancer." (PMID 38900575, 2024). "In obese individuals, higher levels of leptin are produced by fat cells, contributing to pro-cancer effects." (PMID 38534979, 2024). "A common adipokine to influence cancer growth is leptin, which is secreted by adipocytes and regulates systemic energy homeostasis." (PMID 39284708, 2024). "In many cancers, the mTOR pathway is upregulated, possibly due to the dysregulated presence of leptin." (PMID 39596205, 2024). "Leptin can also promote the expression and secretion of IL-18 in TAMs through NF-κB/NF-κB1, thereby fostering the expression and proliferation of cancer cells through the PI3K-AKT/ATF-2 pathway." (PMID 39192979, 2024). "Given the role of leptin signaling in promoting and regulating angiogenesis, the potential for leptin-based therapeutics in addressing angiogenic disease and aberrant angiogenic processes is being studied in both cancer and non-cancer contexts." (PMID 39439572, 2024). "In ER+/PR+ cancer cells, leptin increased autophagy, promoting proliferation and leptin-enhanced mitochondrial metabolism, possibly for maintaining proliferation and cell migration." (PMID 38228661, 2024). "All myokines identified in our study as potentially associated with cancer cachexia are normally released by various cells, predominantly within the immune system (IL-6, IL−8, FABP3) and adipose tissue (leptin, FSTL-1)." (PMID 39411315, 2024). "In summary, the impact of leptin on cancer cell proliferation appears to vary based on the cancer type and the concentration of leptin used in experiments." (PMID 39201370, 2024). "Other peptide receptors (e.g., leptin-derived peptide (Lp31) are known to be expressed in different type of cancers." (PMID 38543324, 2024). "Leptin and adiponectin are reported to have opposite roles in CRC progression, with leptin inducing cancer progression and adiponectin inhibiting tumor growth in vitro." (PMID 38611081, 2024). "Leptin interacts with estrogen pathways through several mechanisms to indirectly promote angiogenic signaling in cancer cells and in the tumor microenvironment." (PMID 39439572, 2024).